TRIM11 (tripartite motif containing 11)
Diseases named in the same sentence as TRIM11 in open-access papers (continued):
Sharing a sentence is not in itself a finding about the gene and the disease.
lymphoma (6 papers, 2021 to 2024). A malignant (clonal) proliferation of B- lymphocytes or T- lymphocytes which involves the lymph nodes, bone marrow and/or extranodal sites. "Conversely, despite the suggested involvement in lymphoma development and the progression of TRIM11, TRIM13, TRIM19, TRIM32, TRIM35, TRIM65, data on their possible function regarding NLRP3 inflammasome regulation are lacking." (PMID 38397043, 2024). "A more recent study demonstrated that an E3 ubiquitin ligase, tripartite motif-containing protein 11 (TRIM11), serves as an oncogene in lymphomas by promoting cell proliferation through activation of the β-catenin signaling." (PMID 35359365, 2022). "On the contrary, TRIM11 overexpression in lymphoma promotes proliferation via the beta-catenin/Wnt pathway." (PMID 36726909, 2022). "A recent study has shown that the ubiquitination of Axin1 by TRIM11 was involved in the carcinogenesis of lymphoma." (PMID 35237324, 2022). "In lymphoma tissue and cell lines in particular, the knockdown of TRIM11 resulted in decreased expression of β-catenin, Cyclin D1, and c-Myc, while Axin1 was increased due to decreased ubiquitin-induced degradation." (PMID 34943200, 2021). "Conversely, when TRIM11 was knocked down in ovarian cancer cells and lymphoma tissues/lymphoma cell lines in vitro, suppression of cell proliferation was observed." (PMID 34943200, 2021). "In addition, it is reported that silencing TRIM11 suppressed β-catenin activity through the ubiquitination of Axin1, thereby attenuating lymphoma, indicating that TRIM11 possesses regulatory effect on Wnt/β-catenin signaling pathway." (PMID 35611828, 2022). "Moreover, it has been reported that TRIM11 is involved in the activation of the β-catenin pathway via the ubiquitination and degradation of Axin1 in lymphomas and that it promotes cell growth and epithelial-mesenchymal transition in gastric cancer by activating β-catenin signaling." (PMID 35237324, 2022).
ovarian carcinoma (6 papers, 2019 to 2022). A malignant neoplasm originating from the surface ovarian epithelium. "Studies have shown that TRIM11 knockout in ovarian cancer cells leads to increased apoptosis or cessation in cell cycle progression." (PMID 36726909, 2022). "TRIM11 is highly expressed in ovarian cancer tissues, and knockout of TRIM11 induces apoptosis of ovarian cancer cells, which indicates that TRIM11 promotes the proliferation of ovarian cancer cells." (PMID 36249749, 2022). "The expression of TRIM11 was found to be significantly increased in ovarian cancer tissues, and knocking down TRIM11 affected the expressions of apoptosis-related proteins (Bcl-2 and Bax) and invasion-related proteins (MMP-2 and MMP-9) and reduced the phosphorylation levels of ERK and AKT." (PMID 36249749, 2022).
colon carcinoma (5 papers, 2016 to 2023). "High expression of TRIM11 (Tripartite Motif-Inplasmid protein 11), an E3 ubiquitin ligase, in colon cancer tissues led to short survival." (PMID 37020597, 2023). "Downregulation of miR-24-3P leads to up-regulation of TRIM11, and TRIM11 can be a therapeutic target for colon cancer." (PMID 37020597, 2023). "To further examine the role of TRIM11, we evaluated its expression in colon cancer tissues by immunohistochemistry (IHC)." (PMID 29581427, 2018). "An analyzing of clinical survival data according to TRIM11 expression levels revealed that high TRIM11 expression correlated with a significantly lower survival probability in colon cancer patients." (PMID 29581427, 2018). "In the present study, we report that expression of TRIM11 was increased in colon cancer (CC) tissue relative to paired normal tissues and that higher TRIM11 levels predicted poor overall survival (OS) and disease-free survival (DFS) in CC patients." (PMID 27888625, 2016). "Interestingly, colon carcinoma tissues expressed TRIM11 at significantly higher levels compared to the normal adjacent tissues." (PMID 29581427, 2018). "TRIM11 is upregulated in colon cancer cells, and it may be co-opted by tumor cells to promote oncogenic growth." (PMID 29581427, 2018). "Moreover, researchers discovered that miR-24 could promote colon cancer cell proliferation, invasion, and migration partially by repressing TRIM11." (PMID 33550881, 2021). "Thus, TRIM11 contributes to tumor progression and may be an important clinical predictor for the survival of colon cancer patients." (PMID 29581427, 2018). "We previously reported that TRIM11 was expressed at higher levels in clinical colon cancer tissues than in adjacent noncancerous tissues, and higher TRIM11 mRNA levels predicted a poor outcome." (PMID 32382014, 2020).
melanoma (5 papers, 2021 to 2026). A malignant, usually aggressive tumor composed of atypical, neoplastic melanocytes. "The differential diagnosis includes cellular blue nevi, perivascular epithelioid cell neoplasm, melanocytic tumors with CRTC1::TRIM11 fusions, melanoma, and epithelioid malignant peripheral nerve sheath tumor." (PMID 39420989, 2024). "CRTC1::TRIM11 cutaneous tumors are an emerging subset of MITF pathway-activated neoplasms that typically present as dermal nodules and can closely mimic clear cell sarcoma or malignant melanoma." (PMID 42015602, 2026). "Routine melanoma-focused next-generation sequencing (NGS) panels do not typically include CRTC1 or TRIM11, so diagnosis often requires targeted RNA sequencing or fusion-based NGS assays." (PMID 41536371, 2025). "TRIM11 immunohistochemistry may also have some value as a screening tool for CMTCT; however, TRIM11 has not been examined in melanoma and other dermal proliferations with melanocytic differentiation." (PMID 34943200, 2021).
osteosarcoma (5 papers, 2018 to 2024). A usually aggressive malignant bone-forming mesenchymal neoplasm, predominantly affecting adolescents and young adults. "TRIM11 is upregulated in osteosarcoma cells and promotes cell proliferation while inhibiting apoptosis." (PMID 39062505, 2024). "The oncogenic role of TRIM11 in osteosarcoma cells can be significantly blocked by the extracellular signal-regulated kinase 1/2 (ERK1/2) inhibitor PD98059." (PMID 39062505, 2024). "TRIM11 commonly acts as an oncogene in various cancers, including osteosarcoma." (PMID 39062505, 2024). "However, the specific role of TRIM11 is still uncovered in human osteosarcoma (OS) cells." (PMID 31950060, 2019).
tauopathies (5 papers, 2023 to 2025). "Importantly, TRIM11 has been linked to the onset of progressive supranuclear palsy (PSP), a prevalent form of sporadic tauopathy, wherein TRIM11 single nucleotide polymorphisms are associated with disease." (PMID 40285004, 2025). "Supporting a general role for TRIM11 in human tauopathies, brain samples from 23 sporadic AD brains showed a marked reduction in TRIM11 protein expression when compared to 14 age- and sex-matched healthy controls." (PMID 40285004, 2025). "All these exceptional activities of TRIM11 would strongly maintain tau in its soluble state and prevent the progress of tauopathies." (PMID 38161205, 2024). "The exceptional study performed by Zhang and colleagues creatively unraveled an invaluable capacity of TRIM11 in the prevention of tauopathies and systematically evaluated the potential of TRIM11 as a therapeutic target." (PMID 38161205, 2024). "The functional multipotency of TRIM11 endows it with the capacity to prevent and treat tauopathies via multiple pathways simultaneously." (PMID 38161205, 2024). "As such, TRIM11 displays remarkable therapeutic potential as an anti-tauopathies weapon to fight AD and other neurodegenerative tau disorders." (PMID 38161205, 2024). "TRIM11 (class IV), meanwhile, has been attributed roles in the establishment of tauopathies AD and progressive supranuclear palsy (PSP, the most common cause of atypical Parkinsonism)." (PMID 38115822, 2023). "The multifaceted ways TRIM11 prevents tauopathies suggests TRIM proteins may be valuable countermeasures to treat CNS disorders." (PMID 40285004, 2025). "The TRIM11 gene has a role in protection against tauopathies, and downregulation could contribute to behavioral problems." (PMID 39202342, 2024). "In a recent paper, TRIM11 was seen to be downregulated in the brains of AD patients and disease phenotypes in different mouse tauopathy models could be rescued by TRIM11 overexpression." (PMID 38115822, 2023). "Since both AD and PSP are tauopathies, a similar mechanism might apply to PSP and therefore TRIM11 is expected to be downregulated in PSP brains." (PMID 40465013, 2025).
glioblastoma (4 papers, 2017 to 2021). The most malignant astrocytic tumor (WHO grade IV). "Another E3 ligase, TRIM11, also regulates EGFR levels and TRIM11 expression correlated closely with glioblastoma stem cell (GSC) markers Nestin and CD133 and promoted tumorsphere formation." (PMID 33324551, 2020). "Knockdown of TRIM11 inhibits proliferation and migration of glioblastoma cells; it's also necessary for the activation of EGFR and MAPK pathways." (PMID 29254187, 2017). "Knockdown of TRIM11 significantly inhibited the transcription of DUSP6 in D-54 glioblastoma multiforme (GBM) cells." (PMID 31950060, 2019).
malignant glioma (4 papers, 2016 to 2023). A grade III or grade IV glioma arising from the central nervous system. "TRIM11 (tripartite motif-containing protein 11), is an E3 ubiquitin ligase and high expression of TRIM11 correlates with malignant glioma cells." (PMID 29254187, 2017). "In addition, TRIM11 is upregulated in malignant gliomas, where it promotes proliferation, invasion, migration, and tumor growth by increasing the accumulation of EGFR and activity of MAPK cascade." (PMID 27888625, 2016).
progressive supranuclear palsy (4 papers, 2018 to 2025). A rare late-onset neurodegenerative disease characterized by supranuclear gaze palsy, postural instability, progressive rigidity, and mild dementia. "An intronic variant of the tripartite motif-containing protein 11 (TRIM11) has been linked to the classic and more aggressive phenotype of progressive supranuclear palsy, Richardson’s syndrome." (PMID 31950334, 2020). "In addition, variants in TRIM11 were identified as a genetic modifier of the PSP phenotype when comparing PSP with Richardson syndrome to PSP without Richardson syndrome." (PMID 39152475, 2024).
cervical cancer (3 papers, 2020 to 2024). A primary or metastatic malignant neoplasm involving the cervix. "For example, in cervical cancer, the TRIM11 mRNA’s stability is enhanced by IGF2BP1 depending on m6A modification, which is mediated by METTL14 and accelerates cervical cancer progression by mediating PHLPP ubiquitination." (PMID 39557826, 2024). "The expression of NEDDL4, RNF6, MDM2 and TRIM11 is abnormal in cervical cancer." (PMID 32655987, 2020).
clear cell sarcoma (3 papers, 2024 to 2026). A rare malignant neoplasm with melanocytic differentiation characterized by the presence of polygonal or spindle shaped clear cells. "In both CRTC1::TRIM11 and MITF::CREM tumors, clear cell sarcoma poses the most challenging differential diagnosis due to their striking similarities." (PMID 39264472, 2024). "In contrast, similar to EWSR1::ATF1 fusion in clear cell sarcoma, both CRTC1::TRIM11 and MITF::CREM fusions likely lead to MITF overexpression through the induction of the CREB signaling cascade." (PMID 39264472, 2024).
virus infection (3 papers, 2013 to 2016). "Since TRIM11 associates with HIV-1 capsid during virus infection, we hypothesized that TRIM11 might induce premature uncoating once it recognizes viral capsid." (PMID 27737691, 2016). "Importantly, the PLA assay showed that TRIM11 associates with HIV-1 capsid during viral infection." (PMID 27737691, 2016). "We then revealed that TRIM11 accelerates HIV-1 uncoating during viral infection in both HEK293 cells and THP-1-derived macrophages." (PMID 27737691, 2016). "Similar to the results involving the ectopic expression of TRIM11, endogenous TRIM11 also decreased with lower levels of Vpr+ virus infection but increased with higher levels of infection." (PMID 25105968, 2014). "Compared with Vpr−, Vpr+ virus infection down-regulated TRIM11 protein levels at lower concentrations while it up-regulated these levels at higher concentrations." (PMID 25105968, 2014). "IFNβ-containing culture media were obtained from 293T cells transfected with a RIG-I signaling component (MAVS or TBK1) and TRIM11 or empty vector, and then used to treat Vero cells prior to viral infection with HSV-1 or VSV-GFP." (PMID 23675467, 2013). "To investigate whether TRIM11 could interact with HIV-1 capsid during virus infection, we introduced the proximity ligation assay (PLA) system that detects protein–protein interactions closer than 40 nm in situ." (PMID 27737691, 2016). "However, we cannot rule out the possibility that the inhibition of reverse transcripts was partially sustained by the mutant TRIM11 at this concentration of viral infection." (PMID 25105968, 2014). "As expected, the results showed that Vpr+ virus infection profoundly decreased TRIM11 protein levels, beginning at 4 h post-inoculation, indicating that the effects of Vpr during HIV-1 infection may not depend on viral genome integration and transcription." (PMID 25105968, 2014). "Furthermore, the inhibition rates of TRIM11 on Vpr− and Vpr+ virus infection were nearly equal." (PMID 25105968, 2014).
breast tumor (2 papers, 2022 to 2024). "TRIM11 deficiency in an animal model represses the growth of breast tumor and stabilizes KDM5C." (PMID 36192394, 2022).
gastric cancer (2 papers, 2022 to 2024). A primary or metastatic malignant neoplasm involving the stomach. "In vitro experiments using human gastric cancer cells HGC-27 demonstrated that TRIM11 overexpression enhanced cell proliferation, migration, and invasion, while its knockdown had the opposite effects." (PMID 39768197, 2024). "Collectively, these findings underscore that TRIM11 contributes to gastric cancer progression by strengthening β-catenin activity through targeted degradation of Axin1, thereby driving tumor growth and invasiveness." (PMID 39768197, 2024). "Upon TRIM11 silencing in gastric cancer cells AGS and SGC-7901, both EGFR and AKT showed decreased expression levels, indicating that it plays a role in the activation of the AKT signaling pathway." (PMID 39768197, 2024). "Mechanistically, another study indicated that TRIM11 can destabilize Axin1 and promote its degradation via ubiquitination, resulting in the β-catenin pathway activation in gastric cancer cells and lymphoma cells." (PMID 39768197, 2024). "The role of TRIM11 in the growth, proliferation, and invasion of gastric cancer cells was observed by a series of cell functional experiments and further verified in vivo." (PMID 35237324, 2022). "Next, the follow-up data of these 150 patients were summarized to further assess the relationship between TRIM11 expression levels and clinicopathological features of gastric cancer patients." (PMID 35237324, 2022). "TRIM11 was upregulated in gastric cancer tissues of patients." (PMID 39768197, 2024). "In vivo, TRIM11 knockdown significantly reduced tumor growth in a subcutaneous xenograft model using BALB/c nude mice, highlighting its oncogenic role in gastric cancer progression via activation of the β-catenin signaling pathway." (PMID 39768197, 2024).
HIV-1 infection (2 papers, 2014 to 2016). The type species of lentivirus and the etiologic agent of acquired immunodeficiency syndrome (AIDS). "Cells bearing TRIM11-HA or control vector were treated with MG132 (proteasomal inhibitor) or chloroquine (lysosomal inhibitor) followed by HIV-1 infection." (PMID 27737691, 2016). "The fate-of-capsid assay indicated that TRIM11 overexpression reduced the level of assembled viral capsid by about 30 % at 1 h post HIV-1 infection." (PMID 27737691, 2016). "To determine the effects of Vpr on endogenous TRIM11 levels, we repeated the HIV-1 infection dose-course and time-course experiments in the HEK293 cells." (PMID 25105968, 2014). "The RING-deleted mutant TRIM11 showed the full restoration of HIV-1 reverse transcripts at 50 ng/ml (p24gag) of HIV-1 infection, suggesting that the RING-domain of TRIM11 is necessary for restricting the early steps of HIV-1 transduction." (PMID 25105968, 2014). "Thus, to investigate the effects of Vpr on TRIM11 during HIV-1 infection, we infected cells that were transiently overexpressing TRIM11 with the HIV-1 Vpr− or Vpr+ virus." (PMID 25105968, 2014). "In contrast with the reductions in viral reverse transcripts, the inhibition of HIV-1 LTR activity was fully sustained by the RING-deleted mutant TRIM11, which may contribute to the marginal reduction of luciferase activity at high levels of HIV-1 infection." (PMID 25105968, 2014). "We observed a clear difference in HIV-1 infectivity between the control and RING-deleted mutant TRIM11 expression cell lines at 75 ng/ml (p24gag) of HIV-1 infection, which may have resulted from the retaining of the inhibition of the mutant TRIM11 on LTR activity." (PMID 25105968, 2014). "To discriminate between the effects of the three TRIM proteins on HIV-1 infection, we compared HIV-1 transduction levels in cells overexpressing TRIM11, TRIM5αrh and TRIM5αhu." (PMID 27737691, 2016).
liver cancer (2 papers, 2020 to 2022). An epithelial or non-epithelial malignant neoplasm that arises from the liver. "We predicted that the patients with liver cancer with high TRIM11 and TRIM55 mRNA expression would have high OS (p = 0.0031 and 0.0044, respectively) and DSS (p = 0.0045 and 0.033, respectively)." (PMID 35142083, 2022).
Lymph Node Metastasis (2 papers, 2022 to 2025). "In contrast to their report, our study revealed that TRIM11 protein expression was an indicator of lymph node metastasis in GC patients." (PMID 35237324, 2022). "The expression of TRIM11 was positively correlated with TNM stage (P=0.04), depth of invasion (P=0.014), and lymph node metastasis (P=0.015)." (PMID 35237324, 2022).
prostate carcinoma (2 papers, 2021 to 2025). A carcinoma that arises from epithelial cells of the prostate gland. "It has been reported that the role of hsa-miR-5193 inhibits the expression of TRIM11, resulting the better OS in prostate cancer, while it suppresses HBV replication." (PMID 33748270, 2021).
thyroid cancer (2 papers, 2022 to 2024). "Furthermore, it is reported that SOX13 is able to trigger TRIM11 transcription by binding 18 bp upstream of transcriptional initiation site of TRIM11 promoter and accelerate thyroid cancer." (PMID 35611828, 2022).
anaplastic thyroid cancer (1 paper, 2021). "Thus, targeting TRIM11 could be a potential strategy or drug target for anaplastic thyroid cancer." (PMID 33613102, 2021).
Anxiety (1 paper, 2022). Intense feelings of nervousness, tension, or panic often arise in response to interpersonal stresses. "Also, TRIM11 can inhibit dopaminergic neuron loss in the substantial nigra and rescue motor impairments caused by α-Syn aggregation; and animals in the TRIM11 group have better locomotor activity and less anxiety." (PMID 35946309, 2022).
Ataxia (1 paper, 2022). Ataxia refers to impaired coordination of voluntary muscle movement. "Among the genes related to cerebellar volume in the four substructure GWASs we find genes related to ataxia (PEX7, MRPS27, PTK2), neurodevelopment (YPEL3, CASP6, TRIM11, GNB5) and microcephaly (PDCD6IP, USP28)." (PMID 35546225, 2022).
chordoma (1 paper, 2021). Chordomas are rare malignant tumors arising from embryonic remnants of the notochord in axial skeleton. "Consistently, TRIM11 is a component in PHLPP1/AKT signaling pathway in human chordoma cells." (PMID 33613102, 2021). "Expression of TRIM11 is upregulated in chordomas tissues and promotes chordoma cells proliferation." (PMID 33613102, 2021).